Y_RNA (Y RNA )
Gene: Miscellaneous RNA gene on chromosome 16 (68,474,553 to 68,474,664, reverse strand). Ensembl gene ENSG00000199263.
Homologues: Orthologues: chimpanzee Y_RNA (100% identical), macaque Y_RNA (98% identical). Paralogues in human: RNY1P5 (82% identical), Y_RNA (82% identical), Y_RNA (81% identical), Y_RNA (80% identical), Y_RNA (79% identical), RNY1P6 (79% identical), Y_RNA (78% identical), Y_RNA (77% identical), RNY1 (76% identical), Y_RNA (76% identical), RNY1P1 (75% identical), RNY1P2 (75% identical), and 92 more.